EYA3 (EYA transcriptional coactivator and phosphatase 3)
Description:
Tyrosine phosphatase that specifically dephosphorylates 'Tyr-142' of histone H2AX (H2AXY142ph). 'Tyr-142' phosphorylation of histone H2AX plays a central role in DNA repair and acts as a mark that distinguishes between apoptotic and repair responses to genotoxic stress. Promotes efficient DNA repair by dephosphorylating H2AX, promoting the recruitment of DNA repair complexes containing MDC1. Its function as histone phosphatase probably explains its role in transcription regulation during organogenesis. Coactivates SIX1, and seems to coactivate SIX2, SIX4 and SIX5. The repression of precursor cell proliferation in myoblasts by SIX1 is switched to activation through recruitment of EYA3 to the SIX1-DACH1 complex and seems to be dependent on EYA3 phosphatase activity (By similarity). May be involved in development of the eye.
Synonyms: DKFZp686C132
Tractability: PROTAC: ubiquitination databases record sites on it; its protein half-life has been measured; a small molecule that binds it is known.
Target class: Enzyme; Hydrolase
Gene: Protein-coding gene on chromosome 1 (27,970,344 to 28,088,731, reverse strand). Ensembl gene ENSG00000158161.
Subcellular location: Cytoplasm; Nucleus
Subcellular location (Human Protein Atlas): Nucleoplasm; Centrosome
Pathways (Reactome):
DNA Repair: Recruitment and ATM-mediated phosphorylation of repair and signaling proteins at DNA double strand breaks
Gene Ontology:
Molecular function: histone H2AXY142 phosphatase activity; protein binding; protein tyrosine phosphatase activity
Biological process: double-strand break repair; positive regulation of DNA repair; response to ionizing radiation; anatomical structure morphogenesis; cell differentiation; negative regulation of extrinsic apoptotic signaling pathway in absence of ligand; visual perception; chromatin remodeling
Cellular component: nucleoplasm; nucleus; cytoplasm
Genetic constraint (gnomAD): Loss-of-function variants: 22 observed, 51.55 expected, observed/expected ratio (o/e) 0.43, 90% interval 0.3 to 0.61. The upper end of that interval is the gene's LOEUF score, 0.61, which puts it in group 2 of 6, group 1 being the genes least tolerant of losing a copy. Missense variants: 406 observed, 544.48 expected, observed/expected ratio (o/e) 0.75, 90% interval 0.69 to 0.81. Synonymous variants: 161 observed, 190.45 expected, observed/expected ratio (o/e) 0.85, 90% interval 0.74 to 0.96.
Homologues: Orthologues: chimpanzee EYA3 (100% identical), rabbit EYA3 (97% identical), dog EYA3 (97% identical), pig EYA3 (96% identical), rat Eya3 (95% identical), macaque EYA3 (92% identical), mouse Eya3 (87% identical), guinea pig EYA3 (84% identical), tropical clawed frog eya3 (69% identical), zebrafish eya3 (56% identical), Drosophila melanogaster eya (39% identical), Caenorhabditis elegans eya-1 (20% identical). Paralogues in human: EYA4 (53% identical), EYA1 (52% identical), EYA2 (44% identical).